ALK (ALK receptor tyrosine kinase)
Diseases named in the same sentence as ALK in open-access papers (continued):
Sharing a sentence is not in itself a finding about the gene and the disease.
non-small cell lung carcinoma (continued). "Pembrolizumab is the drug of choice in the first-line treatment of patients with a PD-L1 expression in >50% of tumor cells in patients with non-small cell lung carcinoma without the EGFR or ALK mutation." (PMID 33435596, 2021). "Moreover, they have shown potential to guide individualized therapy choice, as was illustrated by the detection of different ALK fusion mRNAs with high sensitivity and specificity in patients with non-small cell lung cancer." (PMID 33593440, 2021). "The screening of non-small cell lung cancer (NSCLC) tumors for anaplastic lymphoma receptor tyrosine kinase (ALK) gene rearrangements is important because of the dramatically favorable therapy response to ALK inhibitor." (PMID 34234236, 2021). "ALK rearrangement is responsible for about 3-6% of all non-small cell lung cancers." (PMID 32876329, 2021). "ALK fusion partners are identified as driver events in nearly twenty different human malignancies, including non-small cell lung cancers (NSCLC), anaplastic non-Hodgkin lymphoma, diffuse large B cell lymphoma, renal carcinoma, thyroid cancers, breast cancer, ovarian carcinoma, leukemia, and MM6–8." (PMID 33731690, 2021). "Non-small cell lung cancer models that harbour EGFR mutations and ALK rearrangements have demonstrated induction of PD-L1 expression and reduction of PD-L1 when treated with targeted therapies such as EGFR and ALK inhibitors." (PMID 33956842, 2021). "Ventana ALK D5F3 CDx assay (Ventana ALK (D5F3) CDx Assay, Ventana Medical Systems, Tucson, AZ, U.S.A.)has been approved by the FDA as a companion diagnostic and predictive kit for using crizotinib in patients with non-small cell lung cancer." (PMID 35008368, 2021). "Consequently, in August 2011, the US Food and Drug Administration (FDA) approved crizotinib for the treatment of ALK-positive non-small-cell lung cancer patients (NSCLC)." (PMID 34832908, 2021). "Non-small cell lung cancer (NSCLC) patients with KRAS mutations and ALK rearrangement could benefit from SHP2 inhibitor combo therapy." (PMID 34217295, 2021). "On 24 October 2016, the FDA expanded its approval as the first-line treatment for metastatic non-small-cell lung cancer with high PDL-1 expression (≥ 50%) but no EGFR or ALK mutation (Category 1 and preferred; category 2B if PDL-1 1–49%)." (PMID 32245016, 2020). "In addition, immunohistochemical ALK (D5F3) testing was performed in another 898 patients with non-small cell lung cancer." (PMID 32429938, 2020). "Ceritinib is approved for the treatment of patients with Anaplastic lymphoma kinase (ALK)-positive metastatic non-small cell lung cancer (NSCLC) but can also inhibit the insulin receptor (INSR), the insulin-like growth factor 1 receptor (IGF1R) and ROS proto-oncogene 1 (ROS1)." (PMID 32224911, 2020). "The first-generation anaplastic lymphoma kinase (ALK)-tyrosine kinase inhibitor (TKI) crizotinib has multiple kinase inhibitory activities against ALK, MET, and ROS1, and it shows promising efficacy for non-small-cell lung cancer (NSCLC) patients carrying the ALK gene rearrangement." (PMID 32041944, 2020). "To date, no head-to-head trials have compared the efficacy of brigatinib and alectinib against anaplastic lymphoma kinase (ALK) rearrangement-positive (ALK-p), ALK-inhibitor-naïve, advanced non-small cell lung cancer (NSCLC) with central nervous system (CNS) metastasis." (PMID 32290309, 2020). "Despite inducing strong clinical responses, inhibitors that target abnormal activities of oncogenic tyrosine kinases (TKIs), including those directed against oncogenic ALK signaling in non-small cell lung cancers (NSCLCs), are rarely curative in advanced disease." (PMID 32409712, 2020). "ALK-positive tumors are sensitive to ALK tyrosine kinase inhibitors (TKIs), thus ALK-positive non-small-cell lung cancer (NSCLC) is currently spearheading precision medicine in thoracic oncology, with three generations of approved ALK inhibitors in clinical practice." (PMID 32872120, 2020).
non-small cell lung carcinoma (continued). "Consequently, it is difficult to copy the success of the translational therapies based on genetic alterations in certain types of cancers, such as the EGFR or ALK-driven non-small cell lung cancer." (PMID 33037176, 2020). "Notably, the ALK small molecule inhibitors have been more evaluated in ALK+ solid tumors such as EML4-ALK+ non-small cell lung cancer." (PMID 31340850, 2019). "Nowadays, molecular testing in advanced non-small cell lung cancer (NSCLC) patients includes screening for targetable alterations, e.g., EGFR mutations or ALK rearrangements, and, in addition, factors predictive of response to immunotherapy, thus, immune checkpoint inhibitors (ICIs)." (PMID 31374957, 2019). "Rizzo S found that a pleural effusion related to ALK mutations while nodules located in non-tumour lobes or round lesion shapes were related to a KRAS mutation in subgroups of non-small cell lung cancer patients." (PMID 31215432, 2019). "Besides, the phase III ALUR study directly compared alectinib with chemotherapy in crizotinib-pretreated ALK-positive non-small cell lung cancer." (PMID 31023335, 2019). "The ATLANTIC trial reported that higher PD-L1 expression in tumors was involved in a higher objective response in patients with EGFR+/ALK+ non-small cell lung cancer (NSCLC), indicating the possibility of anti-PD-1/PD-L1 therapy as a third-line (or later) treatment for advanced NSCLC." (PMID 31747941, 2019). "For example, research in the field of radiogenomics have sought to differentiate imaging features of different molecular subtypes of non-small cell lung cancer (NSCLC) based on specific driver mutations, including anaplastic lymphoma kinase (ALK) or epithelial growth factor receptor (EGFR)." (PMID 31781977, 2019). "INSR, has been used as a biomarker for prognosis of non-small cell lung cancer and an INSR protein inhibitor, Zykadia, has been authorized by U.S. Food and Drug Administration (FDA) and European Medicines Agency as a treatment of advanced ALK-positive non-small cell lung cancer." (PMID 30913233, 2019). "ALK fusions occur in ~3% of non-small cell lung cancer (NSCLC)." (PMID 30886831, 2019). "Genomic sequencing of tumor DNA has changed the therapeutic landscape for non squamous, non small cell lung cancer (NSCLC) with the discovery of recurrent oncogenic driver mutations in EGFR, ALK, and ROS‐1 that can be specifically and effectively targeted by new drugs." (PMID 30773851, 2019). "For ALK-positive non-small cell lung cancer (NSCLC), both conditions appear to occur." (PMID 30875928, 2019). "In this case study, a non-small cell lung cancer patient harboring EML4-ALK demonstrated an initial response to treatment with Crizotinib, but subsequently demonstrated resistance following the acquisition of the ALK C1156Y mutation (top left)." (PMID 30675517, 2019). "The choice of the first-line treatment for ALK-positive, non-small cell lung cancer needs to take into account cost–benefit considerations and the patient-reported quality of life, as the treatment sequence did not cause a significant difference in overall survival." (PMID 30699985, 2019). "For example, ALK inhibitors such as crizotinib or ceritinib are used for different neoplasms with an over-activated ALK kinase (usually caused by an EML4-ALK rearrangement) such as neuroblastoma, non-small-cell lung carcinoma or anaplastic large cell lymphoma." (PMID 30223473, 2018). "ALK-rearrangement may predict favorable response to the therapy of bevacizumab plus pemetrexed in advanced non-small-cell lung cancer." (PMID 29318404, 2018). "In order to identify genes and pathways whose inhibition synergizes with crizotinib to induce cell death in ALK rearranged non-small cell lung cancer, we performed a genome-wide RNAi-based synthetic lethal screen in two ALK+ NSCLC adenocarcinoma cell lines, H2228 and H3122." (PMID 29507657, 2018).
non-small cell lung carcinoma (continued). "Alectinib is a highly selective tyrosine kinase inhibitor of anaplastic lymphoma kinase (ALK) and provided a significantly prolonged progression-free survival compared with chemotherapy in patients with advanced non-small cell lung cancer (NSCLC) harboring rearrangements of the ALK gene." (PMID 29524063, 2018). "Numerous clinical trials show crizotinib has promising efficacy for anaplastic lymphoma kinase (ALK) positive non-small cell lung cancer (NSCLC) patients which trigger the substitution of traditional chemotherapy to be the current standard first-line treatment for these patients." (PMID 29088872, 2017). "Alectinib (Alecensa®) is a small molecule kinase inhibitor which has received FDA accelerated approval for the treatment of patients with anaplastic lymphoma kinase (ALK)-positive metastatic non-small cell lung cancer (NSCLC) who have progressed on or are intolerant to crizotinib treatment." (PMID 28261547, 2017). "The ALK gene has been found to be rearranged, mutated, or amplified in a series of tumors including anaplastic large cell lymphomas (ALCL), neuroblastoma, and non-small cell lung cancer (NSCLC)." (PMID 29189709, 2017). "The PPV for the 3 microRNAs was higher than 80%, which indicated that a non-small cell lung cancer patient with low plasma levels of any 1 of the 3 microRNAs was more likely to have ALK-positive disease compared with a patient with high plasma levels of the 3 microRNAs." (PMID 28514730, 2017). "Then, we will discuss the current knowledge about its role in the treatment of ALK-associated cancers, especially in ALK-positive Anaplastic Large Cell Lymphoma (ALCL), ALK-positive Non-Small Cell Lung Carcinoma (NSCLC), Neuroblastoma (NB) and Rhabdomyosarcoma (RMS)." (PMID 29186933, 2017). "EML4/ALK fusion is present in about 5% of patients with non-small cell lung cancer (NSCLC)." (PMID 27926493, 2017). "Over the last few years, studies have demonstrated the occurrence of autophagy in different Anaplastic Lymphoma Kinase (ALK)-associated cancers, notably ALK-positive anaplastic large cell lymphoma (ALCL), non-small cell lung carcinoma (NSCLC), Neuroblastoma (NB), and Rhabdomyosarcoma (RMS)." (PMID 29186933, 2017). "The identification of ALK rearrangements, found in approximately 5% of non-small-cell lung cancers (NSCLCs), and the success of tyrosine-kinase inhibitors (TKI) (crizotinib, ceritinib, alectinib and brigatinib), have provided a breakthrough similar to the discovery of EGFR mutations and treatment." (PMID 28938646, 2017). "Furthermore, one trial of crizotinib reported a remarkable response rate and prolonged progression-free survival among patients with ALK-positive non-small cell lung cancer (NSCLC)." (PMID 27518729, 2016). "Our analysis clearly indicates that CID 11562217, a nitrile containing compound (pyrazole-substituted aminoheteroaryl), could be the potential ALK inhibitor certainly helpful to overcome the drug resistance in non-small cell lung cancer." (PMID 28330089, 2016). "One important success story is the treatment of non-small-cell lung cancer with ALK inhibitors." (PMID 27105842, 2016). "Generally, ALK is identified as tyrosine kinase target in non-small-cell lung cancer." (PMID 27872133, 2016). "Non-small-cell lung cancer (NSCLC) cell lines bearing EGFR, KRAS, BRAF, ALK or RET mutations were found with high level of PD-L1 expression, and this may be correlated with high levels of PI3K/AKT/mTOR pathway activation." (PMID 26919108, 2016). "None of the patients underwent tests for EGFR mutation, KRAS mutation, or ALK gene rearrangement, although 9 of the patients had non-small cell lung cancer of nonsquamous histology." (PMID 27445531, 2016). "Thus, the IGF-1R signaling axis is a potential therapeutic target in ALK-positive non-small cell lung cancer." (PMID 27144340, 2016).
non-small cell lung carcinoma (continued). "In addition to lymphatic tissue tumor, ALK rearrangements can also be detected in other malignancies, including inflammatory myofibroblastic tumors, non-small cell lung cancers, neuroblastomas and embryonal rhabdomyosarcomas." (PMID 27612448, 2016). "Clinical outcomes of anaplastic lymphoma kinase (ALK)-rearranged non-small cell lung cancer according to ALK fusion variants are not clear." (PMID 27756333, 2016). "For example, imatinib, which targets breakpoint cluster region-abelson (BCR-ABL), is used to treat patients with chronic myelogenous leukemia and crizotinib, which targets anaplastic lymphoma kinase (ALK), is used to treat patients with ALK-positive non-small cell lung cancer." (PMID 26497678, 2016). "Rearrangements of the ALK gene are present in 3% to 5% of non-small cell lung cancers (NSCLCs)." (PMID 25889062, 2015). "Although many molecular genetic studies indicate that there are some genetic mutations in non-small cell lung cancer (NSCLC), including EGFR, KRAS, PIK3CA, BRAF, ALK, DDR2, and PDGFRA, only a few studies have focused on the genetic events of salivary gland-type lung carcinomas." (PMID 26575266, 2015). "Most information currently available on the clinical efficacy and causes of relapse on crizotinib treatment are collected in the context of EML4-ALK-positive non-small-cell lung cancer, which is the most common ALK-related disease, whereas little is known about other ALK-positive malignancies." (PMID 25727400, 2015). "The antitumour activity of crizotinib in cancer clinical trials has been significant, leading to the Food and Drug Administration (FDA) approval as an integral addition to clinical treatment of patients with non-small cell lung cancer (NSCLC) carrying ALK translocations." (PMID 26445453, 2015). "For example, the National Comprehensive Cancer Network (NCCN) guidelines for non-small cell lung cancer (NSCLC) recommend measurement of genomic alterations in seven different genes (EGFR, ALK, ERBB2 (encodes HER2 protein), BRAF, MET, ROS1 and RET) to guide twelve different matched therapies." (PMID 26474073, 2015). "Companion diagnostics associated with favourable drug responses comprised genomic alterations in non-small cell lung cancer (EGFR mutations and ALK rearrangements), breast and gastric cancers (HER2/neu amplification or overexpression), and in melanoma (B-RAF mutation)." (PMID 26446908, 2015). "ALK testing and subsequent targeted therapy could be an effective option for patients with non-small cell lung cancer who present progression following chemotherapy, radiotherapy, or any other treatment." (PMID 24885608, 2014). "In that case the sponsor was proposing that the subset of “ALK-positive non small cell lung cancer” could be considered as a distinct orphan medical condition." (PMID 24461084, 2014). "In previous studies, ALK was involved in tumor progression of several cancers, including anaplastic large cell lymphomas, ALK-positive diffuse large B-cell lymphomas, inflammatory myofibroblastic tumors, and non-small cell lung carcinomas." (PMID 25193856, 2014). "The most impressive clinical effects observed with HSP90 inhibitor monotherapy have arisen in defined subsets of tumors that exhibit a high degree of oncogenic dependence on particular client proteins e.g., ALK-driven non-small cell lung cancer and HER2-amplified breast cancer." (PMID 24682747, 2014). "In addition TFG has been identified as a putative metastatic melanoma tumour suppressor gene and is also thought to play a role in non-small cell lung cancer, acting as a translocation partner for anaplastic lymphoma kinase (ALK)." (PMID 24999993, 2014). "However, recent studies have demonstrated that epithelial malignancies can also harbor recurrent gene fusions, including ETS rearrangements in prostate cancer and EML4/ALK in non-small cell lung cancer." (PMID 23637631, 2013).
non-small cell lung carcinoma (continued). "Many translocations have been found with this ALK gene, including EML4:ALK which is responsible for approximately 3-5% of non-small-cell lung cancer(NSCLC), RANBP2:ALK, TPM4:ALK in inflammatory myofibroblastic tumor, NPM1:ALK, ATIC:ALK, TFG:ALK in anaplastic large cell lymphoma, and so on." (PMID 24564548, 2013). "Non-small cell lung carcinoma patients harboring ALK gene rearrangement have been reported to benefit from tyrosine kinase inhibitor treatment, which makes the reliable screening of ALK fusions important." (PMID 23484153, 2013). "However, meanwhile acquired crizotinib resistance in ALK+ non-small cell lung carcinomas was observed." (PMID 22911523, 2012). "The ALK gene has gained much attention due to the association between ALK-positive tumors that may be found in various types of cancer including diffuse large B-cell lymphoma (DLBCL), non-small-cell lung cancer (NSCLC), and anaplastic large-cell lymphoma (ALCL)." (PMID 41471783, 2025). "Crizotinib is an anti-cancer medication approved by the FDA in January 2021 for non-small cell lung carcinoma (NSCLC) treatment through the inhibition of both anaplastic lymphoma kinase (ALK) and c-ros oncogene 1 (ROS1)." (PMID 39860235, 2025). "In cancers such as non-small-cell lung cancer (NSCLC), well-characterised genetic signatures have transformed management with tyrosine kinase inhibitors targeting EGFR mutations and next-generation ALK inhibitors addressing ALK mutations, resulting in significantly improved patient outcomes." (PMID 39727715, 2024). "For example, the systemic treatment of advanced non-small cell lung cancer remained conventional chemotherapy for several decades until the emergence of TKI therapy following the discovery of several driver mutations including EGFR, ALK, ROS1, MET, RET, BRAF, and ERBB2/HER2." (PMID 39409947, 2024). "CHECKMATE 816 was the first phase 3 study to evaluate neoadjuvant nivolumab plus chemotherapy in patients with resectable stage IB–IIIA non-small cell lung cancer (per the AJCC seventh edition staging system) with no epidermal growth factor receptor (EGFR)/ALK mutations." (PMID 38731161, 2024). "In patients with non-small cell lung cancer, 95.84% of the pharmaceutical antineoplastic expenditure was explained by four therapeutic groups: immunotherapy (33.74%), drugs targeting EGFR-activating mutations (28.36%), pemetrexed (22.16%), and ALK tyrosine kinase inhibitors (11.58%)." (PMID 37754495, 2023). "Alectinib is first-line therapy in patients with stage IV non-small cell lung carcinoma (NSCLC) and an anaplastic lymphoma kinase (ALK) fusion." (PMID 36969063, 2023). "Combining TALEN and SCNT techniques, pigs simulating human non-small cell lung cancer were developed and achieved time–space and site-specific expression of the mutant proteins through rearrangement of echinoderm microtubule-associated protein 4 (EML4) and anaplastic lymphoma kinase (ALK) genes." (PMID 36325365, 2022). "Considering the evolving treatment landscape for ALK+ non-small cell lung cancer (NSCLC), more data are needed for brigatinib in both the post-crizotinib and post-next generation settings, which could help clinicians make informed decisions and maximize patient benefits." (PMID 35781589, 2022). "In addition, non-small cell lung cancer (NSCLC) patients with activating mutations, such as epidermal growth factor receptor mutations (EGFR) or anaplastic lymphoma kinase (ALK) translocations, may have longer survival than wild-type patients." (PMID 33498505, 2021). "Notably, tissue samples obtained using this technique can undergo tests for epidermal growth factor receptor (EGFR) mutations and immunohistochemical screening for anaplastic lymphoma kinase (ALK) rearrangement in patients with non-small cell lung cancer (NSCLC)." (PMID 33963234, 2021).